LINC00273 (long independently transcribed non-coding RNA 273)
Synonyms: TOP; NCRNA00273-1; NCRNA00273
Gene: Long non-coding RNA gene on chromosome 16 (34,158,585 to 34,160,036, reverse strand). Ensembl gene ENSG00000256642.
Diseases named in the same sentence as LINC00273 in open-access papers:
LINC00273 is named in the same sentence as 2 diseases in open-access papers, as found by Europe PMC text mining. Sharing a sentence is not in itself a finding about the gene and the disease. The quoted sentences say what the papers report.
cancer (2 papers, 2017 to 2021). A tumor composed of atypical neoplastic, often pleomorphic cells that invade other tissues. "LINC00273, as an inducer of metastasis, which significantly inhibits epithelial to metastasis and mesenchymal transition, promotes cancer metastasis." (PMID 34070941, 2021).
LINC00273 also shares sentences with these, for which no sentence is quoted: tumor (1 paper).